BCL2 (BCL2 apoptosis regulator)
Diseases named in the same sentence as BCL2 in open-access papers (continued):
Sharing a sentence is not in itself a finding about the gene and the disease.
cancer (continued). "BCL-2 protein expression is found to be elevated in various cancers." (PMID 39519400, 2024). "However, with the depth of the study, high expression of anti-apoptotic proteins such as BCL-2, which leads to the apoptotic escape of cancer cells, has been considered another significant mechanism." (PMID 39319052, 2024). "Cancer cells often evade apoptosis by boosting anti-apoptotic BCL-2 proteins." (PMID 39229580, 2024). "In summary, our findings suggest that BTZ’s potential anti-cancer efficacy could be largely attributed to its influence on the caspase-8-Bid-Bax/Bcl-2 mitochondrial pathway." (PMID 38724504, 2024). "MYC gene overexpression can sometimes sensitize cancer cells to BCL-2 inhibitor-induced apoptosis." (PMID 38756697, 2024). "Moreover, this activation of STAT3 enhances the expression of anti-apoptotic proteins, such as Bcl-2, Bcl-XL, and Mcl-1, in cancer cells, thereby increasing resistance to cell death." (PMID 38510850, 2024). "Indeed, the balance between Bcl-2 and Bax expression acts as a regulator for cell survival in response to apoptotic stimuli by altering the apoptotic threshold for cancer cells." (PMID 38802425, 2024). "Cancer cells employ various mechanisms to suppress apoptosis, including upregulation of anti-apoptotic proteins like B-cell lymphoma 2 (Bcl-2), B-cell lymphoma-extra large (Bcl-xL), and Myeloid leukemia 1 (Mcl-1), and downregulation of pro-apoptotic proteins such as Bax and Bim." (PMID 39000577, 2024). "The activation of AKT can regulate the proliferation, differentiation, invasion, migration and apoptosis of cancer cells by regulating downstream protein factors, such as B-cell leukaemia lymphoma-related protein gene (Bax), anti-apoptosis protein Bcl-2 and cysteine protease." (PMID 39301883, 2024). "Furthermore, PKM2 can also enter mitochondria to phosphorylate BCL2 (an apoptosis regulator), thus facilitating cancer cell adaptation to oxidative stress." (PMID 38627278, 2024). "The comparative interaction analysis denoted that PSP binds to most of the amino acids with which the Venetoclax inhibitor interacts, suggesting PSP’s potential to act as an inhibitor of the Bcl-2 protein, thereby promoting apoptosis and the death of cancer cells." (PMID 39598781, 2024). "Another study on the same cancer cells explained that ORI‐N more significantly retarded tumor proliferation by causing G2/M‐phase cell cycle arrest and induced apoptosis through BCL‐2/BAX pathway in a concentration‐dependent way, when compared with ORI solution." (PMID 38726411, 2024). "Also significantly raises the rate at which cancer cells express BCL-2, BAX, caspases, and the PI3K-AKT-mTOR signaling pathway." (PMID 39605919, 2024). "Moreover, CuONPs inhibited cell growth and induced apoptosis in various cancer cells by regulating the expression of BCL-2, BAX, and CCND1." (PMID 38813193, 2024). "Here, we demonstrated the Bcl-2-dependent modulation of genes associated to Hippo Pathway and regulation of core proteins upstream to YAP in cancer cell lines from different histotypes, and the functional significance of this novel cellular signal regulation mediated by Bcl-2." (PMID 38755629, 2024). "Therefore, inhibition of Bcl-2 inactivation has become a highly attractive strategy in the battle against cancer, and BH3 mimetics are the main category of promising therapeutic agents." (PMID 39840282, 2024). "CypD may also suppress cell death pathways, thereby promoting cancer cell survival, by binding and restricting the release of pro-apoptotic factors like Bcl-2 or by suppressing necrosis in response to oxidative stress." (PMID 38573968, 2024). "Thus, indicating that Yap inhibition by Verteporfin is able to revert fibroblast activation induced by cancer-specific Bcl-2." (PMID 38755629, 2024).
cancer (continued). "Numerous research studies have provided evidence that the abundance of Bcl-2 is higher in malignant cells, suggesting that suppressing Bcl-2 expression could be a viable therapeutic approach for cancer treatment." (PMID 38978121, 2024). "In the investigation of the anticancer properties of hawthorn’s active ingredients, the researchers discovered that chlorogenic acid and hyperoside can modify the Bax/Bcl-2 ratio, resulting in a significant induction of apoptosis and displaying their therapeutic potential in cancer treatment." (PMID 38915462, 2024). "Conversely, the increased expression of Bcl-2 in other extracts could be explained by cancer cells attempting to counteract the treatment’s effects by enhancing their resistance to apoptosis." (PMID 38987732, 2024). "Additionally, Bifidobacterium demonstrates an effect on the apoptotic resistance of cancer cells through activation of pro-caspases, upregulation of Bax proteins, and downregulation of anti-apoptotic Bcl-2, although exact mechanisms are poorly understood." (PMID 39189761, 2024). "The study reported a comprehensive anticancer mechanism of eugenol against cancer cell lines, involving the promotion of translocation of the pro-apoptotic gene Bax, a decrease in the anti-apoptotic gene Bcl-2, the release of cytochrome c, and the activation of caspase-9 and caspase-3." (PMID 39416730, 2024). "Additionally, using combined proteomic, CNA data, and whole-exome, we systematically examined pathway-level somatic alterations in Bcl2, implicating vital pathways across various cancer types." (PMID 38223131, 2024). "Disrupting the relationship between HMGB1 and Beclin-1/Bcl-2 may be an effective way to regulate autophagy, thus inhibiting the survival of cancer cells." (PMID 37897664, 2024). "Moreover, we detected the expression of CCDC113, MMP2 (associated with migration and invasion of cancer cells), BAX and BCL2 in CCDC113 overexpression cells and control cells." (PMID 39261464, 2024). "Bcl2 and Bcl-XL inhibit the loss of mitochondrial membrane potential mediated by Granzyme B, Bcl-XL, and BNIP3, as well as caspase-mediated apoptosis, thereby promoting cancer cell survival." (PMID 39518013, 2024). "Other studies have shown that polyphenols induce apoptosis in cancer cells by targeting Bcl-2." (PMID 38473728, 2024). "Potential targets associated with cancer were HMG-CoA reductase, Bcl-2, Mcl-1, and VEGFR-2." (PMID 39769118, 2024). "Z24 is one of the molecules belonging to the 3-substituted indolin-2-ones class of compounds having anti-cancer and anti-angiogenic properties, that could block BCL2 based on in silico analysis." (PMID 38928195, 2024). "The extract might induce apoptosis in cancer cells, as shown by the Bcl-2 and Bcl class signaling pathways." (PMID 38629020, 2024). "Moreover, EGCG demonstrated a decrease in the expression of anti-apoptotic proteins, specifically BCL-2, across multiple cancer cell lines." (PMID 38978121, 2024). "Furthermore, BCL2, an oncogenic gene that plays an anti-apoptotic role in cancer and drives its progression, demonstrated an incrementally enhanced regulatory score from normal B cells to BLS3, lending further credibility to our inference." (PMID 38184630, 2024).
cancer (continued). "Overexpression of proteins such as B-cell lymphoma 2 (Bcl-2), inhibitor of apoptosis proteins (IAPs), protein kinase B (Akt), and P-glycoprotein (P-gp) in various cancers leads to resistance by inhibiting apoptosis, enhancing cell survival, and expelling drugs." (PMID 39274842, 2024). "Their findings suggest that Bcl-2 is more expressed in the lamina propria of low-grade cancers." (PMID 38785951, 2024). "According to the authors, this mechanism could be linked to BCL-2’s modulatory effects on cancer cell proliferation and the coexistence of other BCL-2 family proteins, such as Bax, which may counterbalance BCL-2’s effect." (PMID 39685591, 2024). "Therefore, inhibition or downregulation of the anti-apoptotic BCL-2 proteins is an attractive target for an effective cancer therapy." (PMID 40150937, 2024). "However, cancer cells acquire resistance to cell death by overexpressing prosurvival proteins, including BCL-2, BCL-xL, and BCL-w, while downregulating pro-apoptotic ones." (PMID 38893134, 2024). "However, cancer cells often activate pro-survival signaling pathways such as Bcl-2, HIF-1, AMPK, NRF2, NF-kB, and AKT-TOR to adapt and survive the treatment, which can lead to PDT resistance." (PMID 39494340, 2024). "Moreover, 2-HG, by exerting an inhibitory effect on cytochrome C oxidases, contributes to increasing the expression of the anti-apoptotic protein B-cell leukemia/lymphoma 2 protein (BCL-2) in cancer cells, which ultimately leads to a reduction in apoptosis." (PMID 39063158, 2024). "Furthermore, the newly synthesized enones induced cell death in cancer cells through apoptosis by promoting changes in cellular morphology, activating apoptotic regulators Bax and caspase 3, and inhibiting Bcl-2." (PMID 39463485, 2024). "In numerous scenarios, such as cancer, suppressing Bcl-2 is vital to counteract apoptosis." (PMID 38169388, 2024). "In subsequent years, Hurley and colleagues identified a cholestane derivative as a strong and specific i-motif binding compound, which may provide an approach to regulate BCL2 transcription in cancer cells." (PMID 39407611, 2024). "Bcl-2 and its family members are prime molecular targets for developing new cancer therapeutics." (PMID 38329389, 2024). "When cancer cells are treated with nanoformulations, Bax activation and Bcl-2 downregulation occur." (PMID 38622436, 2024). "Therefore, there have been various attempts to treat cancers through regulating the Bcl2 expression." (PMID 38892434, 2024). "Overexpression of BCL-xL and BCL-2 play key roles in tumorigenesis and cancer drug resistance." (PMID 38548768, 2024). "B-cell-lymphoma-2 (BCL2) homology-3 (BH3) mimetics are inhibitors of protein–protein interactions (PPIs) that saturate anti-apoptotic proteins in the BCL2 family to induce apoptosis in cancer cells." (PMID 39025942, 2024). "BCL2 and its family members control apoptosis and play important roles in many cancers." (PMID 38877653, 2024). "The mechanisms include inhibiting apoptosis by upregulating anti-apoptotic genes such as BCL-2, therefore protecting cancerous cells from programmed cell death and enhancing various transporters and proteins that lead to multidrug resistance in cancer." (PMID 39766121, 2024). "Resveratrol modulates BAX and BCL-2, critical apoptosis regulators, impacting cancer cell survival." (PMID 39769099, 2024). "Many types of cancer exhibit proliferative inflammatory atrophy in adjacent tissues, a condition resulting from inflammation and cellular damage that leads to the upregulation of the cell death regulatory protein Bcl-2." (PMID 38542202, 2024). "Specifically, Bcl-2 overexpression leads to cancer progression and resistance to cancer therapies." (PMID 38329389, 2024).
cancer (continued). "We hypothesized that small molecules targeting the Bcl-2 that switch its function to a pro-death protein can be developed to effectively treat cancers that express Bcl-2." (PMID 38329389, 2024). "In this study, we developed a method combining random forest algorithms, molecular docking, and molecular dynamics simulations to screen small molecules that could potentially inhibit BCL2, a known target in cancer therapy." (PMID 38785951, 2024). "In addition to its inhibitory role, RA potentiates the activation of the Bax pathway by inhibiting Bcl-2, thereby increasing cancer cell apoptosis." (PMID 38324801, 2024). "Past research shows high Bcl-2 levels can impart chemotherapy resistance in cancer cells." (PMID 38622436, 2024). "Also, a morphological analysis of the lymph nodes and a molecular docking study using three proteins related with cancer as targets, namely, Bcl-2, Mcl-1 and VEGFR-2, were performed." (PMID 38731446, 2024). "Notably, the synergistic approach, employing simultaneous administration of multiple miRNAs, led to a significant decrease in cancer cell survival, correlated with reduced Bcl-2 expression." (PMID 38543296, 2024). "However, in cancer, this pro-apoptotic effect is countered by the overexpression of anti-apoptotic proteins such as Bcl-2, Bcl-xL, and HK, which interact with VDAC1." (PMID 39456237, 2024). "Bcl-2 inhibitors have demonstrated considerable potential as a therapeutic intervention for malignancies, with favorable outcomes both as monotherapy and in conjunction with other pharmacological agents across a wide range of malignancies." (PMID 38978121, 2024). "Indeed, a drug class, called BH3-mimetics, have been developed to directly target BCL2 proteins and promote cancer cell death." (PMID 38549077, 2024). "This comparative interaction analysis indicates that PSP binds to most of the amino acids with which the Venetoclax inhibitor interacts, suggesting PSP’s potential to act as an inhibitor of the Bcl-2 protein, thereby promoting apoptosis and the death of cancer cells." (PMID 39598781, 2024). "Moreover, we succeeded in isolating key interactions in the activation of Bak and inhibition of Bcl-2 proteins that trigger the mechanisms of apoptosis and cell death in cancer cells." (PMID 39598781, 2024). "Consequently, targeting the bcl-2 gene and its protein product through chemotherapeutic agents has emerged as a pivotal cancer treatment strategy." (PMID 39624842, 2024). "Therefore, inhibition of bcl-2 mRNA can induce sensitivity to antitumor therapies, and delivery of this shRNA into cancer cells is a promising gene therapeutic approach." (PMID 39319107, 2024). "Finally, molecular docking studies were performed using cancer-associated proteins as targets, including HMG-coA reductase, Bcl-2, Mcl-1, and VEGFR-2." (PMID 39769118, 2024). "Conversely, overexpression of BCL-2 inhibits apoptosis and promote the survival of cancer cells." (PMID 38813193, 2024). "Thus, fucoidan from Fucus vesiculosus has been shown to induce apoptosis in cancer cells by downregulating Bcl-2 and upregulating Bax, while also enhancing the phagocytic activity and cytokine production of macrophages." (PMID 39407623, 2024). "ITCs possess the capability to counteract heparin's suppression of Bax and enhancement of Bcl‐2, implying that ITCs may exert an anticancer effect by fostering the apoptosis of cancer cells." (PMID 39479720, 2024).
cancer (continued). "In WTs, POU2F3-positive cells tended to be on the abluminal side when two layers were recognizable and, at least partly, co-expressed p63 and p40, common abluminal markers, along with KIT and BCL2, which are often expressed in carcinomas with tuft cell-like phenotype." (PMID 38358561, 2024). "Accordingly, increased levels of BCL-2 expression have been correlated with resistance to several anti-cancer drugs, including 5-fluorouracil, adriamycin and mitomycin, in gastric cancer, cisplatin in ovarian cancer and doxorubicin in osteosarcoma and chondrosarcoma." (PMID 36342579, 2023). "In cancer cells, Myc increases cell viability by overexpressing Bcl2 and NF-κB." (PMID 38186581, 2023). "Most studies link BAK1 as well as BCL2 with the regulation of cancer." (PMID 37576599, 2023). "Similar to Bax and Bcl-2, c-Myc and cyclin D1 have been suggested as prognostic factors in cancer." (PMID 37064948, 2023). "Our findings showed that BHE and betanin can stimulate the intrinsic and extrinsic apoptosis pathways in HT-29 and Caco-2 cancer cell lines via downregulation of Bcl-2 and upregulation of BAD and Caspase-9 genes and also upregulation of Fas-R, Caspase-3, and Caspase-8, respectively." (PMID 37464362, 2023). "For example, most solid cancer cells cannot be efficiently killed by BCL-XL or BCL-2 inhibition, but their inhibition may sensitize cancer cells to various chemotherapy or immunotherapy." (PMID 39872303, 2023). "Interestingly, new findings on a rat model of colon carcinoma revealed the key role of B-cell lymphoma-2 (Bcl-2) overexpression in cancer escape from immune surveillance." (PMID 37233460, 2023). "Moreover, the Bax/Bcl-2 ratio has a clinical significance in the prognosis of patients with cancer and the development of resistance to chemotherapeutic agents." (PMID 37064948, 2023). "miR-195 is involved in the regulation of cancer by targeting Cyclin D1, BCL-2, and YAP1." (PMID 38136338, 2023). "Recent studies have suggested that inhibition of αVβ5 integrin may affect the expression of the anti-apoptotic protein Bcl-2 in cancer cells." (PMID 37568817, 2023). "The Bcl-2 protein controls cell migration and invasion, resulting in cancer metastasis." (PMID 38138165, 2023). "The interaction of RAS and Bcl-2 was demonstrated in cancer cells in the last century." (PMID 36967521, 2023). "Consequently, targeting the inactivation of Bcl-2 to enhance apoptosis sensitivity holds great promise for cancer treatment." (PMID 37637038, 2023). "Therefore, anticancer reagents targeting BCL2‐regulated apoptosis expand treatment options for cancers." (PMID 37357618, 2023). "As a result, BCL2, which is overexpressed in many cancers, blocks apoptosis and autophagy." (PMID 37308913, 2023). "It has also been shown that survivin/Bax/Bcl-2 signaling is involved in the apoptosis of cancers." (PMID 37108785, 2023). "While these results are promising, Bcl-2 may have limited utility as a cardioprotective agent for cancer-therapy-induced cardiac toxicity." (PMID 37759797, 2023). "Indeed, we found that THCs displayed higher expression levels of pro-survival BCL-2 relative to parental macrophages or cancer cells." (PMID 37848444, 2023).